TRAC (T cell receptor alpha constant)
Description:
Constant region of T cell receptor (TR) alpha chain. Alpha-beta T cell receptors are antigen specific receptors which are essential to the immune response and are present on the cell surface of T lymphocytes. Recognize peptide-major histocompatibility (MH) (pMH) complexes that are displayed by antigen presenting cells (APC), a prerequisite for efficient T cell adaptive immunity against pathogens. Binding of alpha-beta TR to pMH complex initiates TR-CD3 clustering on the cell surface and intracellular activation of LCK that phosphorylates the ITAM motifs of CD3G, CD3D, CD3E and CD247 enabling the recruitment of ZAP70. In turn, ZAP70 phosphorylates LAT, which recruits numerous signaling molecules to form the LAT signalosome. The LAT signalosome propagates signal branching to three major signaling pathways, the calcium, the mitogen-activated protein kinase (MAPK) kinase and the nuclear factor NF-kappa-B (NF-kB) pathways, leading to the mobilization of transcription factors that are critical for gene expression and essential for T cell growth and differentiation. The T cell repertoire is generated in the thymus, by V-(D)-J rearrangement. This repertoire is then shaped by intrathymic selection events to generate a peripheral T cell pool of self-MH restricted, non-autoaggressive T cells. Post-thymic interaction of alpha-beta TR with the pMH complexes shapes TR structural and functional avidity.
Synonyms: TCRA; IMD7; TRCA
Gene: T-cell receptor constant (C) gene on chromosome 14 (22,547,506 to 22,552,156, forward strand). Ensembl gene ENSG00000277734.
Subcellular location: Cell membrane
Gene-disease validity (ClinGen):
ClinGen rates the evidence that TRAC causes each of these diseases.
TCR-alpha-beta-positive T-cell deficiency (autosomal recessive): Moderate. A non-severe combined immunodeficiency disorder manifesting with recurrent respiratory infections, candidiasis, diarrhea, and failure to thrive.
Homologues: Orthologues: tropical clawed frog trac (31% identical). Paralogues in human: TRAV1-2 (10% identical), TRAV24 (10% identical), TRAV1-1 (9% identical), TRAV20 (9% identical), TRAV36DV7 (9% identical), TRAV26-2 (9% identical), TRAV13-1 (8% identical), TRAV30 (8% identical), TRAV4 (8% identical), TRAV5 (8% identical), TRAV6 (8% identical), TRAV21 (7% identical), and 9 more.
Diseases named in the same sentence as TRAC in open-access papers:
TRAC is named in the same sentence as 36 diseases in open-access papers, as found by Europe PMC text mining. Sharing a sentence is not in itself a finding about the gene and the disease. The quoted sentences say what the papers report.
graft versus host disease (6 papers, 2019 to 2024). An immune system disorder that occurs after allogeneic hematopoietic stem cell transplant and is a reaction of donor immune cells against host tissues. "Though these genetic disruptions to the HLA loci, CIITA, TRAC, and PD-1 present on T cells serve to mitigate the effects of graft-versus-host disease, there remains a life-threatening risk of graft-versus-host disease." (PMID 39835140, 2024). "Current techniques knock out the T cell receptor α constant (TRAC) and CD52 genes/loci to reduce the risk of graft-versus-host disease (GvHD) and to avoid a host-versus-graft reaction, respectively." (PMID 38779672, 2024). "In BCMA 1-R2 CAR T-cells, the TRAC gene was eliminated by transcription activator-like effector nucleases (TALEN)-knockout strategy to reduce the potential of graft-versus-host disease (GvHD)." (PMID 33504363, 2021). "This includes the design of universal CAR T cells with reduced potential for both initiating graft-versus-host disease (GVHD) and eliciting donor T-cell rejection, through targeted disruption of the endogenous T-cell receptor (TRAC) and beta-2 microglobulin (B2M), respectively." (PMID 31727131, 2019). "CRISPR/Cas9 has also been used to disrupt the TRAC and B2M genes to generate ‘universal’ allogeneic CAR T cells that knock out the endogenous TCR and HLA class-1 molecules, respectively, thereby limiting graft-versus-host-disease (GVHD) and immune rejection by T cells in patients." (PMID 38882639, 2024).
leukemia (5 papers, 2019 to 2026). A malignant (clonal) hematologic disorder, involving hematopoietic stem cells and characterized by the presence of primitive or atypical myeloid or lymphoid cells in the bone marrow and the blood. "eSHS6-CAR T cells maintained robust anti-tumor activity even after multiple leukemia rechallenges and demonstrated proliferation, persistence, and tumor clearance similar to T-Cell Receptor Alpha Constant (TRAC)-CAR T cells." (PMID 41511364, 2026). "It has been shown that deletion of T Cell Receptor Alpha Constant (TRAC), B2M, and PDCD1 in universal EGFRvIII and CD19-CAR-T cells enhanced their anti-tumor responses, respectively, against both solid and hematologic malignancies (glioblastoma and leukemia)." (PMID 36419058, 2022). "Noticeably, TRAC gene plays a key role in regulating the mutual killing effect of CAR-T cells, therefore targeted silencing of this gene may promotes the therapeutic effect of CAR-T cells on leukemia." (PMID 39422621, 2024).
acute lymphoblastic leukemia (2 papers, 2020 to 2023). Leukemia with an acute onset, characterized by the presence of lymphoblasts in the bone marrow and the peripheral blood. "For example, the UCART7 product for CD7+ acute lymphocytic leukemia (ALL) uses clustered regularly interspaced palindromic repeat (CRISPR)/Cas9 editing to simultaneously eliminate the endogenous T cell receptor alpha constant (TRAC) and CD7 genes, preventing GVHD and fratricide, respectively." (PMID 37654497, 2023). "Moreover, knocking out CD7 and TRAC in CAR T cells increased the efficacy in the treatment of T cell acute lymphoblastic leukemia (T ALL)." (PMID 33117331, 2020).
combined immunodeficiency (2 papers, 2025 to 2026). A broad classification of inherited disorders presenting at birth that affect both the cell-mediated and humoral aspects of the immune response. "To date, only five patients from three unrelated families harboring the same TRAC variant with a CID phenotype, and three patients carrying a distinct variant with severe combined immunodeficiency (SCID), have been described." (PMID 41882383, 2026).
glioma (2 papers, 2019 to 2024). A benign or malignant brain and spinal cord tumor that arises from glial cells (astrocytes, oligodendrocytes, ependymal cells). "The immune clusters with multitumor contributions corresponded to macrophages (C3, MSR1) and T cells (C21, CD247, and TRAC), while C31 cells were microglia of glioma with multipatient contributions, and C41 cells were Kupffer cells of ICC with multipatient contributions." (PMID 38010945, 2024). "Following stimulation with EGFRvIII-expressing glioma, we demonstrated that both control (i.e., T cells edited for TRAC and B2M, without CAR) and CART-EGFRvIII cells (i.e., T cells edited for TRAC and B2M, with CAR) were positive for surface PD-1 by flow cytometry." (PMID 31727131, 2019).
Immunodeficiency (2 papers, 2021 to 2023). Failure of the immune system to protect the body adequately from infection, due to the absence or insufficiency of some component process or substance. "“TRAC” is a protein coding gene related to immunodeficiency." (PMID 36733434, 2023). "It has been reported that TRAC mutations cause a human immunodeficiency disorder characterized by a lack of TCR αβ + T cells." (PMID 34083506, 2021).
Allergy (1 paper, 2020). An allergy is an immune response or reaction to substances that are usually not harmful. "TRAC is another important mediator that exacerbates allergy reactions with the infiltration of eosinophils and Th2 cells, as well contributing to various diseases induced by mast cell activation." (PMID 33256200, 2020).
Artemis deficiency (1 paper, 2024). "Sixpatients had ADA deficiency, 3 had IL2RG deficiency, 3 had CD3 Delta deficiency, 2 had Artemis deficiency (affecting DCLRE1C), and 1 each had variants impacting NHEJ1, TRAC, RAC2, and RMRP." (PMID 39062699, 2024).
lentivirus infection (1 paper, 2023). Virus diseases caused by the Lentivirus genus. "Comparing CAR-T cells that with functional TRAC locus (conventional CAR-T, made by lentivirus infection), IRU CAR-T cells had significantly lower frequency of IFNγ producing cells." (PMID 38123592, 2023).
liver fibrosis (1 paper, 2025). "MF2 cells specifically expressed liver fibrosis-related genes AGTR1, CYGB, PIEZO2, and LPL, and MF5 cells specifically highly expressed immune-related genes TRAC, CD3D, GZMB, and FCGR3A." (PMID 40949143, 2025).
melanoma (1 paper, 2025). A malignant, usually aggressive tumor composed of atypical, neoplastic melanocytes. "We defined clusters corresponding to melanoma (PMEL, MLANA), immune infiltrates (TRBC2, TRAC, TMSB4X), melanophages (CD74, LYZ), keratinocytes (KRT14, TRIM29), blood vessels (CAVIN1, PECAM), and fibroblast‐enriched areas in the dermis (DCN, COL1A2, FBLN1)." (PMID 39846232, 2025).
R17 (1 paper, 2016). "Based on the phenotypic and biochemical results, candidates for specific Par protein binding included TraI and the second key factor involved in pilus specific R17 phage infection, T4CP TraD, as well as the VirB4-like ATPase TraC, which is essential for assembly and function of R1 pili." (PMID 27486582, 2016).
T-cell lymphoma (1 paper, 2015). "The dysregulation of the mTORC2 pathway is further validated by the observed down-regulation of TCR components (TRAC, TRBC1) and stabilizing molecules (TRAT1) seen across multiple T-cell lymphoma subtypes." (PMID 26566034, 2015).
tumor (28 papers, 2019 to 2026). "To define tumor‐associated lymphocytes interacting with Carcinoma 3, we subclustered T lymphocytes based on the expression of CD3D and TRAC, yielding a total of 21,093 cells (nBCC = 6191, nSCCIS = 7981, and nSCC = 6921)." (PMID 40776410, 2025). "We locate human T cells as cells expressing high PTPRC, CD2, and TRAC and observe areas within the tumor with high variability in the degree of infiltration." (PMID 40081369, 2025). "Our results therefore highlight the potential of targeting the transferrin–T cell receptor α constant (TRAC) interaction as a novel LM therapeutic strategy and the vital role of the constant domain (CD) in anti-tumor immunity." (PMID 39810853, 2025). "Previous studies placing a tumor-reactive receptor under transcriptional control of the TRAC locus used xenograft mouse models in which tumor burden was reduced by adoptive T-cell transfer, but the tumors could not be fully removed." (PMID 30877233, 2019). "Our data show that targeting a TCR to the TRAC locus and placing it under the transcriptional control of the endogenous regulatory network redirects the specificity of the modified T cells and enables them to specifically eliminate tumor cells in vitro and in a murine in vivo tumor xenograft model." (PMID 30877233, 2019). "Our analyses revealed that CXCL9+ macrophage-rich immune cell niches were accumulated in the tumor-liver invasive margin, where 2 subclasses of the CXCL9+ immune cell niches, CXCL9+TRAC+ (CT) and CXCL9+C1QB+ (CC) niches, were identified." (PMID 41766656, 2026). "Studies have shown that CAR-T cells engineered through CRISPR-mediated knockin at T-cell receptor alpha constant (TRAC) loci exhibit consistent CAR expression, enhanced anti-tumour efficacy and persistence." (PMID 39726634, 2024). "Multiplexed knockout of TRAC, B2M, and PD-1 in CD19-specific CAR-T cells demonstrated enhanced anti-tumor activity and reduced alloreactivity, offering promise for more accessible, universal CAR-T therapies." (PMID 39726634, 2024). "To enhance NK cell anti-tumor reactivity, we knocked-in a CAR that targets epidermal growth factor receptor (αEGFR-CAR) to the TRAC locus." (PMID 34162850, 2021). "Subsequently, the same group showed that ZFN-based single editing of the TRAC locus and lentiviral TCR transduction was sufficient to produce safe and highly active tumor-targeted T cells, with a protocol more amenable to clinical translation." (PMID 32570906, 2020). "This seminal paper provided the proof of concept that disruption of the endogenous TRAC and TRBC loci significantly enhances the safety (by abrogating TCR mispairing), avidity and anti-tumor function of TCR locus edited T cells." (PMID 32570906, 2020). "In this study, we identified a novel strategy that inhibits TCR activation, in which transferrin directly binds to TRAC to inhibit the formation of the TCR–CD3 signaling complex, block TCR signaling, and consequently suppress anti-metastatic and anti-tumor immunity." (PMID 39810853, 2025). "Tumour infiltrated T cells expressed TRAC, IL7R, CD8A, and were negative for naïve T cell marker CCR7." (PMID 38267611, 2024). "The in vitro antitumor function of these multiplex double‐knockout (DKO) (TRAC and B2M) and triple‐knockout (TKO) (TRAC, B2M, and PD‐1) CAR‐T cells revealed higher cytokine production and potent cytotoxic activity against tumor cells compared to standard CAR‐T cells." (PMID 34188916, 2021). "Mechanistically, transferrin directly interacts with TRAC with a high affinity of 10.9 nM to interfere with TCR–CD3 complex interaction to suppress TCR activation and anti-tumor immunity, while blocking transferrin–TRAC interaction inhibited metastasis and showed significant anti-tumor effects." (PMID 39810853, 2025). "In contrast, TRAC-KO cells failed to infiltrate into the tumor." (PMID 37349298, 2023).
cancer (9 papers, 2020 to 2025). A tumor composed of atypical neoplastic, often pleomorphic cells that invade other tissues. "For example, CRISPR has been employed to insert CAR in the T-cell receptor alpha constant (TRAC) locus and to delete several genes, including PD-1, to improve antitumor effect in various cancer models." (PMID 37908590, 2023). "Among the 5,343 identified general translocations, ~200 genes involved in various cancer pathways were observed to fuse with the TRAC, TRBC, or PDCD1 gene." (PMID 35260581, 2022). "Two genes encoding the endogenous T cell receptor (TCR) chains, TRAC and TRBC, were deleted in T cells to reduce TCR mispairing and to enhance the expression of a synthetic, cancer specific TCR transgene (NY-ESO-1)." (PMID 33014853, 2020). "A first-in-human phase 1 clinical trial has recently published the safety and feasibility of deleting three genes (TRAC, TRBC, and PDCD1, the gene encoding PD-1) using CRISPR-Cas9 in cancer-specific T cells for the treatment of patients with refractory cancer." (PMID 32625204, 2020). "CRISPR/Cas9 engineered T cells showed high efficiency and safety in cancer immunotherapy, we therefore explored the potential usage of SynCRISPR-Cas3 for genome editing in human cells by disrupting T-cell receptor α constant (TRAC) locus in CD3+ T cells." (PMID 38750051, 2024). "Autologous T cells collected from three cancer patients were modified using Cas9 RNPs targeting TRAC, TRBC, and PDCD1 genes and further engineered with a lentivirus carrying an HLA‐A2*0201‐restricted TCR specific to cancer antigens NY‐ESO1 and LAGE‐1 to generate engineered T cells, called NYCE." (PMID 39156766, 2024). "In this study, researchers disrupted the TRAC, TRBC, and PD1 genes to enhance antitumor immunity and introduced a cancer-targeting transgene, NY-ESO-1." (PMID 40481182, 2025). "In the first clinical report of the use of SpCas9 to edit genes in human cells, three genes (TRAC, TRBC, and PDCD1) were subject to ex vivo editing in primary human T cells, which were subsequently expanded and infused into cancer patients." (PMID 34162850, 2021).
infection (2 papers, 2008 to 2021). The state of being infected such as from the introduction of a foreign agent such as serum, vaccine, antigenic substance or organism. "To this end, we transduced Jurkat cells with SE and SE-IS2 (in-LTR) IDLVs at a multiplicity of infection (MOI = 4) in order to obtain homogenous eGFP positive cells prior to nucleofection using CRISPR/Cas9 to target the T cell receptor alpha chain (TRAC) coding region." (PMID 34452178, 2021).
TRAC also shares sentences with these, for which no sentence is quoted: Behçet disease (1 paper); beta thalassemia (1); breast carcinoma (1); Burkitt lymphoma (1); cardiac ischemia (1); cardiovascular disease (1); glioblastoma (1); hematologic malignancies (1); myeloid tumor (1); narcolepsy (1); narcolepsy type 1 (1); pancreatic cancer (1); parasitemia (1); primary ciliary dyskinesia (1); primary hyperparathyroidism (1); Sepsis (1); Sickle Cell Anemia (1); thrombocytopenia 1 (1); Wiskott-Aldrich syndrome (1); X-linked severe combined immunodeficiency (1).